SCRIB (scribble planar cell polarity protein)
Diseases named in the same sentence as SCRIB in open-access papers (continued):
Sharing a sentence is not in itself a finding about the gene and the disease.
craniorachischisis (5 papers, 2013 to 2021). Craniorachischisis is the most severe form of neural tube defect in which both the brain and spinal cord remain open to varying degrees. "The SCRIB mutation (p.I285K) which caused craniorachischisis in mice adversely affected SCRIB membrane localization." (PMID 23922697, 2013). "In addition, we demonstrated that the craniorachischisis mouse line-90 mutation I285K, also affected SCRIB subcellular localization." (PMID 23922697, 2013). "In humans, SCRIB mutations are associated with craniorachischisis and several kinds of cancer." (PMID 23922697, 2013). "Among craniorachischisis cases, about 20% have potentially deleterious variants in single PCP genes (VANGL2, CELSR1, SCRIB or DACT1)." (PMID 30134561, 2018). "SCRIB mutations have previously been identified in craniorachischisis patients; however, it is not clear whether SCRIB mutations are associated with non-craniorachischisis types of NTDs in humans." (PMID 23922697, 2013).
gastric cancer (5 papers, 2020 to 2022). A primary or metastatic malignant neoplasm involving the stomach. "Analysis of public data indicates that FAM83H expression is closely associated with SCRIB expression in human gastric cancers." (PMID 32564009, 2020). "In this study, the effect of FAM83H and SCRIB on the proliferation of gastric cancer cells was associated with the canonical Wnt/β-catenin pathway." (PMID 32564009, 2020). "In agreement with data from the public database, FAM83H expression showed a significant association with SCRIB expression in human gastric carcinoma tissue samples." (PMID 32564009, 2020). "In addition, a higher expression of SCRIB was associated with the shorter survival of ovarian and gastric cancer patients." (PMID 35885485, 2022). "In addition, SCRIB induced expression of factors linked to EMT phenotype and increased invasion of gastric cancer cells and cytoplasmic SCRIB increased the invasion activity of liver cancer cells." (PMID 33803371, 2021). "Therefore, this study investigated the roles and associations between FAM83H, SCRIB, and β-catenin in gastric carcinomas using human gastric carcinoma tissues and gastric cancer cells." (PMID 32564009, 2020). "FAM83H overexpression especially activated the tumor growth and pulmonary metastasis of gastric cancer cells, which was attenuated with the knock-down of SCRIB in vivo." (PMID 35885485, 2022). "EMT phenotype, loss of E-cadherin with the induction of N-cadherin and Snail has been induced with the overexpression of FAM83H and SCRIB in gastric cancer cells and ovarian cancer cells." (PMID 35885485, 2022). "A study found that FAM83H and SCRIB synergistically activate gastric cancer progression by stabilizing β-catenin." (PMID 35938024, 2022). "Recently, FAM83H and SCRIB have been presented as important regulators of human cancers, and FAM83H was closely associated with SCRIB in the progression of gastric carcinomas." (PMID 35885485, 2022). "The molecular relationship between FAM83H and SCRIB is evident in data from the public database and is further supported by a study on the relationship between FAM83H and SCRIB in gastric carcinomas." (PMID 35885485, 2022). "Overexpression of SCRIB stimulated invasiveness of gastric cancer cells by stabilizing β-catenin and stimulating the EMT pathway." (PMID 33803371, 2021). "In gastric carcinomas, SCRIB stabilizes β-catenin by binding it and consequently activating TCF/LEF transcription." (PMID 33803371, 2021). "Activation of the FAM83H-SCRIB pathway stimulates the proliferation and invasion of gastric cancer cells, and both FAM83H and SCRIB are involved in the β-catenin-related pathway and the EMT pathway." (PMID 32564009, 2020). "In MKN-45 and NCI-N87 gastric cancer cells, the expression of FAM83H and SCRIB were associated with proliferation and invasiveness of cells." (PMID 32564009, 2020). "Clinicopathologic variables and the expression of FAM83H, SCRIB, and β-catenin in gastric carcinomas." (PMID 32564009, 2020). "Based on the prognostic significance of the expression of FAM83H and SCRIB in gastric carcinoma patients, we performed proliferation and migration/invasion assays after inducing knock-down or overexpression of FAM83H and SCRIB in gastric cancer cells." (PMID 32564009, 2020). "In conclusion, we demonstrate that FAM83H and SCRIB cooperatively activate the progression of gastric carcinoma by stabilizing β-catenin." (PMID 32564009, 2020). "In human gastric carcinomas, both the individual and combined expression patterns of the nuclear FAM83H and SCRIB were independent indicators of shorter survival of gastric carcinoma patients." (PMID 32564009, 2020). "The relationship between FAM83H and SCRIB was also reported in gastric cancers." (PMID 35885485, 2022). "Furthermore, a higher expression of SCRIB also predicted shorter survival of ovarian carcinoma and gastric carcinoma." (PMID 35885485, 2022).
gastric cancer (continued). "Moreover, FAM83H is important in the stabilization of β-catenin in osteosarcoma in our previous study, and a public database indicates a significant correlation between the expression of FAM83H and SCRIB in gastric cancer." (PMID 32564009, 2020). "Therefore, we evaluated the effects of knock-down of SCRIB on gastric cancer cells on inducing the overexpression of FAM83H." (PMID 32564009, 2020). "Therefore, this study investigated the roles of FAM83H and SCRIB in 200 human gastric cancers and gastric cancer cells." (PMID 32564009, 2020). "Based on the characteristic of FAM83H, SCRIB, and β-catenin as components of cell junctions, alteration of FAM83H, SCRIB, and β-catenin might stimulate the progression of gastric carcinomas." (PMID 32564009, 2020). "Moreover, our results indicate nuclear expression of FAM83H and SCRIB as independent indicators of poor prognosis of gastric carcinoma patients." (PMID 32564009, 2020). "In conclusion, this study has found that the individual and combined expression patterns of nuclear FAM83H and SCRIB are prognostic indicators of gastric carcinomas and further suggests that FAM83H and SCRIB are involved in the progression of gastric carcinomas by stabilizing β-catenin." (PMID 32564009, 2020). "Moreover, individual and co-expression patterns of the nuclear FAM83H and SCRIB might be used as novel prognostic markers of gastric cancers." (PMID 32564009, 2020). "Therefore, nuclear expression patterns of FAM83H, SCRIB, and β-catenin and their interactions might be important in the progression of gastric cancers, and their nuclear expression may be of prognostic significance." (PMID 32564009, 2020). "In this respect, FAM83H and SCRIB might be molecular therapeutic targets of gastric carcinomas." (PMID 32564009, 2020). "In gastric carcinomas, FAM83H is involved in the regulation of the expression of SCRIB and forms the FAM83H-SCRIB complex, and FAM83H-SCRIB stabilizes β-catenin to induce EMT and the proliferation of cancer cells." (PMID 35885485, 2022). "Regarding therapeutic application targeting the FAM83H-SCRIB pathway, the knock-down of FAM83H and/or SCRIB inhibited the growth of various human cancer cells, such as hepatocellular carcinoma, gastric carcinoma, ovarian carcinoma, and osteosarcoma." (PMID 35885485, 2022). "In gastric cancer cells, FAM83H and SCRIB stimulated the invasiveness of cancer cells and FAM83H induced pulmonary metastasis in mice transplanted cancer cells with FAM83H overexpression." (PMID 32564009, 2020). "Moreover, FAM83H and SCRIB stimulated the proliferation and invasion of gastric cancer cells, and FAM83H overexpression-stimulated proliferation of gastric cancer cells was attenuated with a knock-down of SCRIB in vitro and in vivo." (PMID 32564009, 2020). "FAM83H and SCRIB stimulate the proliferation and invasiveness of gastric cancer cells, and the expression of SCRIB was dependent on FAM83H expression, but FAM83H was not affected by SCRIB expression." (PMID 32564009, 2020). "Therefore, the FAM83H-SCRIB-β-catenin pathway might be a novel therapeutic target for the poor prognostic subgroups of gastric cancer, which express high levels of FAM83H and SCRIB." (PMID 32564009, 2020). "Furthermore, in this study, during the search for the roles and relationship between FAM83H and SCRIB in gastric carcinomas, we found that both FAM83H and SCRIB form a complex with β-catenin and are involved in post-translational stabilization from proteasomal degradation." (PMID 32564009, 2020).
colorectal cancer (3 papers, 2021 to 2022). A primary or metastatic malignant neoplasm that affects the colon or rectum. "In univariate analysis, the nuclear expressions of FAM83H and SCRIB and the cytoplasmic expression of SCRIB were significantly associated with shorter survival of colorectal carcinomas." (PMID 35885485, 2022). "In the analysis of the public database, there was a significant association between FAM83H and SCRIB in colorectal carcinomas." (PMID 35885485, 2022). "Many studies have confirmed the role of the Hippo signaling pathway in colorectal cancer metastasis, and the specific mechanism, for instance, may be that upregulated SCRIB expression promotes YAP phosphorylation, thereby inhibiting the Hippo pathway." (PMID 35642057, 2022). "However, the role of SCRIB in colorectal cancer (CRC) remains largely unknown." (PMID 33937255, 2021).
hepatocellular carcinoma (3 papers, 2020 to 2022). A malignant tumor that arises from hepatocytes. "In addition, transfection of mutant SCRIB caused a cytoplasmic enriched induced EMT phenotype of hepatocellular carcinoma cells and increased invasiveness of cancer cells." (PMID 33803371, 2021). "However, cytoplasmic localization of SCRIB was detected in 69% (22/32 cases) of hepatocellular carcinomas." (PMID 33803371, 2021). "The expression of SCRIB mRNA was also higher in hepatocellular carcinomas compared with non-tumorous liver tissue." (PMID 32564009, 2020). "In the liver, cytoplasmic localization of SCRIB was higher in hepatocellular carcinoma compared with non-tumorous liver tissue, and cytoplasmic SCRIB induced expression of EMT genes." (PMID 32564009, 2020).
liver cancer (3 papers, 2021 to 2023). An epithelial or non-epithelial malignant neoplasm that arises from the liver. "Equally, the basolateral cell polarity complex protein Scribble (SCRIB) supports liver cancer initiation and migration upon enrichment in the cytosol." (PMID 37381005, 2023). "The cytoplasmic and nuclear expression of SCRIB in liver cancer tissue was supported by Western blots performed with subcellular fractionated protein lysates." (PMID 33803371, 2021). "Furthermore, cytoplasmic and nuclear localization of SCRIB, induced by overexpression of SCRIB, stimulated the proliferation of liver cancer cells." (PMID 33803371, 2021). "In a study with human and mouse liver cancer models, cytoplasmic and nuclear expression of SCRIB was more prevalent in liver cancer tissue, and non-neoplastic liver tissue showed SCRIB expressed solely on the cytoplasmic membrane." (PMID 33803371, 2021).
lung carcinoma (3 papers, 2021 to 2022). "A decreased expression of SCRIB in cancer-associated fibroblasts was associated with shorter survival of lung cancer patients." (PMID 35885485, 2022). "Knock-down of SCRIB in cancer-associated fibroblasts increased invasiveness of both tumor-associated fibroblasts and co-cultured Lewis lung cancer cells." (PMID 33803371, 2021). "However, controversially, higher immunohistochemical expression of SCRIB was associated with favorable prognosis of lung cancer patients." (PMID 33803371, 2021). "Likewise, low expression of SCRIB in fibroblasts seems to be associated with the invasiveness of lung cancer cells." (PMID 34503271, 2021).
prostate carcinoma (3 papers, 2017 to 2022). A carcinoma that arises from epithelial cells of the prostate gland. "Recently, miR-512-5p has been shown to modulate the expression of the apoptosis regulator MCL-1, and miR-296-5p has been demonstrated to reduce cell proliferation of breast and prostate cancer cells by targeting SCRIB or HMGA1, respectively." (PMID 29221158, 2017). "Downregulation of SCRIB could disrupt the epithelial polarity and was strongly correlated with poor survival in prostate cancer patients." (PMID 33294438, 2020).
Verheij syndrome (3 papers, 2018 to 2022). "Mutations in the locus encompassing the SCRIB gene (8q24.3) have been linked to the rare Verheij syndrome (VRJS, OMIM #615583), characterized by severe growth retardation including microcephaly and intellectual disability, and ASD." (PMID 35626639, 2022). "Human SCRIB gene mutations are associated with neural tube defects and this gene is located in the minimal critical region deleted in the rare Verheij syndrome." (PMID 33907211, 2021). "Verheij syndrome is a rare microdeletion syndrome of chromosome 8q24.3 that harbors PUF60, SCRIB, and NRBP2 genes." (PMID 30352594, 2018).
anencephaly (2 papers, 2018 to 2021). A rare neural tube defect during pregnancy, resulting in the absence of a large portion of the brain and skull in the fetus. "Five anencephaly cases carried rare or novel CELSR1 missense variants, three of whom carried additional rare potentially damaging PCP variants: 01F377 (CELSR1 c.6362G>A and PRICKLE4 c.730C>G), 2F07 (CELSR1 c.8807C>T and DVL3 c.1622C>T), 618F05 (CELSR1 c.8282C>T and SCRIB c.3979G>A)." (PMID 29205322, 2018).
coloboma (2 papers, 2018 to 2022). An abnormality in which a part of a structure in one or both eyes is missing. "Also, an exome analysis identified a rare SCRIB variant that resulted in coloboma." (PMID 35692812, 2022). "In examining the prioritized list of rare variants identified in superior coloboma patients, we note rare variants in NKD1, CELSR2, FZD4, SCRIB, and WNT9B (components of canonical or non-canonical Wnt pathways)." (PMID 29522511, 2018).
endometrial carcinoma (2 papers, 2020 to 2021). A malignant tumor arising from the epithelium that lines the cavity of the uterine body. "In a study using tissues from normal endometrium, endometriosis, and endometrial adenocarcinoma, membranous expression of SCRIB in normal endometrium changed to be localized in the cytoplasm and nuclei in endometriosis and endometrial carcinomas." (PMID 33803371, 2021). "In addition, as the degraded membranous components of SCRIB and E-cadherin, the levels of serum-soluble SCRIB and E-cadherin were higher in endometrial cancer patients compared with healthy volunteers." (PMID 32564009, 2020).
lymphoma (2 papers, 2021 to 2022). A malignant (clonal) proliferation of B- lymphocytes or T- lymphocytes which involves the lymph nodes, bone marrow and/or extranodal sites. "Knock-out of SCRIB delayed expansion of B cells in the development of MYC-mediated lymphoma development." (PMID 33803371, 2021). "These molecular relationships might be supported by the report that SCRIB is involved in the initiation of MYC-driven lymphoma." (PMID 33803371, 2021).
microcephaly (2 papers, 2021 to 2022). A congenital or acquired developmental disorder in which the circumference of the head is smaller than normal for the person's age and sex. "Our results support the theory that the microcephaly and ACC observed in VRJS patients is the result, at least partially, of SCRIB haploinsufficiency." (PMID 33907211, 2021). "A case with 8q24.3 deletion including SCRIB showed dysmorphic facial features, cardiac defects, and vertebrate anomalies but no microcephaly, highlighting the complexity of human genetics." (PMID 35692812, 2022).
oropharyngeal squamous cell carcinoma (2 papers, 2021 to 2022). "We investigated how modifications in the cellular localization and protein expression of DLG1 and SCRIB in HPV16-positive and HPV-negative histologic oropharyngeal squamous cell carcinomas (OPSCC) might reflect disease progression." (PMID 34503271, 2021).
ovarian carcinoma (2 papers, 2021 to 2022). A malignant neoplasm originating from the surface ovarian epithelium. "In this study, the expression of SCRIB was associated with advanced clinicopathological factors of ovarian carcinomas, such as elevation of CA125 level, high cancer stage, and higher histologic grade." (PMID 33803371, 2021). "In this study, we demonstrated that SCRIB stimulates proliferation and invasiveness of ovarian cancer cells in conjunction with activation of the factors linked to the EMT pathway." (PMID 33803371, 2021). "Immunohistochemically, SCRIB was expressed in both the cytoplasm and nuclei of ovarian carcinoma cells." (PMID 33803371, 2021). "The proliferation of SKOV3 and SNU119 ovarian cancer cells were significantly inhibited by knockout of SCRIB and significantly stimulated by overexpression of SCRIB as evidenced by CCK8 proliferation assay and colony forming assay." (PMID 33803371, 2021). "In SKOV3 and SNU119 ovarian cancer cells, overexpression of SCRIB stimulated the proliferation and invasion of cells." (PMID 33803371, 2021). "In conclusion, this study presents the nuclear expression of SCRIB as a prognostic marker of ovarian carcinomas and suggests that SCRIB is involved in the progression of ovarian carcinomas by stimulating proliferation and epithelial-to-mesenchymal transition-related invasiveness." (PMID 33803371, 2021). "One of the interesting findings of our study is that SCRIB might be involved in chemoresistance of ovarian cancer cells." (PMID 33803371, 2021). "Therefore, we investigated the roles of SCRIB in ovarian carcinomas in conjunction with the EMT phenotype using human ovarian carcinoma tissues and ovarian cancer cells." (PMID 33803371, 2021). "In addition, the migration and invasion ability of SKOV3 and SNU119 ovarian cancer cells were significantly inhibited by knockout of SCRIB and were significantly stimulated by overexpression of SCRIB as evidence by wound-healing, migration, and invasion assay." (PMID 33803371, 2021). "Thus, this study evaluated the roles of SCRIB in ovarian cancers." (PMID 33803371, 2021). "Furthermore, our results suggest that the SCRIB-EMT pathway might be a new therapeutic target for the ovarian carcinomas which highly express SCRIB and are refractory to the conventional anti-cancer therapies." (PMID 33803371, 2021).
prostate intraepithelial neoplasia (2 papers, 2018 to 2025). A neoplastic proliferation of the epithelial cells that line the acini and the ducts of the prostate gland. "Knockout of SCRIB in the prostate epithelium in mice led to prostate hyperplasia and prostate intraepithelial neoplasia (PIN)." (PMID 39428716, 2025). "For example, conditional knockout of cell polarity protein SCRIB in mouse prostates has been reported to lead to prostatic intraepithelial neoplasia." (PMID 30118484, 2018).
atherosclerosis (1 paper, 2023). A disease characterized by the build-up of fatty material and calcium deposition in the arterial wall resulting in partial or complete occlusion of the arterial lumen. "On the other hand, deletion of Scrib in ApoE-deficient mice impairs vascular permeability and promotes atherosclerosis development, indicating that SCRIB contributes to anti-inflammatory responses in endothelial cells." (PMID 37583551, 2023).
colorectal tumors (1 paper, 2016). "The expression of SCRIB is frequently lost in more advanced tumors and this downregulation results in disrupted cell polarity, amongst others in breast and colorectal tumors." (PMID 27014907, 2016).
emphysema (1 paper, 2017). "Finally, we show that PCP genes VANGL2 and SCRIB are significantly downregulated in lung tissue from patients with emphysema." (PMID 28237967, 2017).
human papillomavirus infection (1 paper, 2021). "Previous work has demonstrated that the Scribble complex members DLG1 and/or SCRIB play key roles facilitating ARHGEF26 activity and RHOG activation during human papillomavirus infection, as well as in regulating epithelial junction formation, contractability, and lumen formation in 3D cysts." (PMID 34242364, 2021).